NFKBIE (NFKB inhibitor epsilon)
Description:
Sequesters NF-kappa-B transcription factor complexes in the cytoplasm, thereby inhibiting their activity. Sequestered complexes include NFKB1-RELA (p50-p65) and NFKB1-REL (p50-c-Rel) complexes. Limits B-cell activation in response to pathogens, and also plays an important role in B-cell development (By similarity).
Synonyms: IKBE
Tractability: PROTAC: ubiquitination databases record sites on it; its protein half-life has been measured.
Target class: Other cytosolic protein
Gene: Protein-coding gene on chromosome 6 (44,258,166 to 44,265,788, reverse strand). Ensembl gene ENSG00000146232.
Subcellular location: Cytoplasm
Subcellular location (Human Protein Atlas): Nucleoli fibrillar center; Cytosol; Nucleoplasm
Pathways (Reactome):
Immune System: Activation of NF-kappaB in B cells
Gene Ontology:
Molecular function: protein binding; protein sequestering activity
Cellular component: cytoplasm; cytosol; fibrillar center; nucleoplasm
Genetic constraint (gnomAD): Loss-of-function variants: 11 observed, 27.81 expected, observed/expected ratio (o/e) 0.4, 90% interval 0.25 to 0.65. The upper end of that interval is the gene's LOEUF score, 0.65, which puts it in group 2 of 6, group 1 being the genes least tolerant of losing a copy. Missense variants: 352 observed, 446.35 expected, observed/expected ratio (o/e) 0.79, 90% interval 0.72 to 0.86. Synonymous variants: 206 observed, 209.8 expected, observed/expected ratio (o/e) 0.98, 90% interval 0.88 to 1.1.
Cancer hallmarks: escaping immune response to cancer; suppression of growth (promotes)
Homologues: Orthologues: chimpanzee NFKBIE (99% identical), macaque NFKBIE (98% identical), dog NFKBIE (88% identical), rabbit NFKBIE (88% identical), pig NFKBIE (87% identical), mouse Nfkbie (82% identical), rat Nfkbie (81% identical), guinea pig NFKBIE (78% identical), tropical clawed frog nfkbie (41% identical), zebrafish nfkbie (40% identical). Paralogues in human: BCL3 (33% identical), POTEB3 (20% identical), POTEI (20% identical), POTEJ (20% identical), POTEB (20% identical), POTEB2 (20% identical), POTEC (19% identical), POTEE (19% identical), POTEF (19% identical), POTED (19% identical), POTEH (19% identical), POTEM (19% identical), and 2 more.
Diseases named in the same sentence as NFKBIE in open-access papers:
NFKBIE is named in the same sentence as 38 diseases in open-access papers, as found by Europe PMC text mining. Sharing a sentence is not in itself a finding about the gene and the disease. The quoted sentences say what the papers report.
melanoma (8 papers, 2016 to 2025). A malignant, usually aggressive tumor composed of atypical, neoplastic melanocytes. "The finding of focal amplifications/promoter mutations of NFKBIE in DM is also of particular interest, providing a window to a distinct mechanism driving this subtype of melanoma." (PMID 26663830, 2016). "Similarly, exome sequencing has also suggested that NFKBIE was highly mutated among melanoma patients." (PMID 28542447, 2017). "A rare histological variant is the desmoplastic melanoma arising on chronic sun-damaged skin and is uniquely characterized by NFKBIE (NFKB inhibitor epsilon) promoter mutation, rare types of BRAF mutation and high tumor mutational burden (TMB)." (PMID 35628196, 2022). "In summary, this study is the first to identify recurrent mutations in NFKBIE, a negative regulator of NFkB, as a partial genomic explanation for response to anti-PD1 immunotherapy in melanoma patients." (PMID 32708981, 2020). "Interestingly, a novel alteration was observed in desmoplastic melanomas, consisting of the recurrent (14.5% of cases) promoter mutation of the NFKB Inhibitor Epsilon (NFKBIE) gene, encoding for an inhibitor of NFκB." (PMID 29156643, 2017). "Using the Illumina Human Bodymap RNA sequencing data, the authors neatly demonstrated that the mutational hotspot was in the promoter region of the short isoform of NFKBIE, which they showed to be ubiquitously expressed in melanoma using data from The Cancer Genome Atlas (TCGA)." (PMID 26663830, 2016). "Mutation of this hotspot region was also demonstrated in two melanoma cell lines (M257 and M375), which were both shown to express the same short isoform of NFKBIE, and showed a lack of NFκB translocation to the nucleus." (PMID 26663830, 2016).
chronic lymphocytic leukemia (5 papers, 2020 to 2024). "Our study confirms similar reports about the effect of NFKBIE variants on NFkB activity in rheumatoid arthritis (RA) and lymphoid malignancies (chronic lymphocytic leukemia (CLL), primary mediastinal B-cell lymphoma (PMBL) and Hodgkin lymphoma (HL))." (PMID 32708981, 2020). "The NFKBIE Y254fs mutation has been reported in aggressive chronic lymphocytic leukemia (CLL), Hodgkin lymphoma (HL), DLBCL, primary mediastinal B-cell lymphoma (PMBCL) and a few cases of low-grade B-cell NHL, including follicular lymphoma (FL), EMZL, and SMZL." (PMID 32585984, 2020). "Loss-of-function mutations in NFKBIE, which encodes for the NF-κB inhibitor IκBε, are frequent in chronic lymphocytic leukemia (CLL) and certain other B-cell malignancies and have been associated with accelerated disease progression and inferior responses to chemotherapy." (PMID 38486128, 2024). "In chronic lymphocytic leukemia (CLL), NFKBIE-mutated cells showed reduced IκBε protein levels and decreased p65 inhibition, along with increased phosphorylation and nuclear translocation of p65." (PMID 36140254, 2022).
lymphoma (5 papers, 2019 to 2023). A malignant (clonal) proliferation of B- lymphocytes or T- lymphocytes which involves the lymph nodes, bone marrow and/or extranodal sites. "Our results also suggested that lenalidomide might relieve relapsed lymphoma with mutations in NFKBIA 202C>T (p.Q68*) and NFKBIE 433A>T (p.K145*) by targeting NF-Kappa B signaling." (PMID 34405005, 2021).
rheumatoid arthritis (5 papers, 2011 to 2022). A chronic, systemic autoimmune disorder characterized by inflammation in the synovial membranes and articular surfaces. "Variants around NFKBIE are reported to be associated with rheumatoid arthritis susceptibility." (PMID 31757224, 2019). "We use molecular interaction and colocalisation analyses to identify multiple nuclear regulatory pathways linking meQTL loci to phenotypic variation, including UBASH3B (body mass index), NFKBIE (rheumatoid arthritis), MGA (blood pressure), and COMMD7 (white cell counts)." (PMID 34980917, 2022). "Association analysis of NFKBIE and RTKN2 with rheumatoid arthritis." (PMID 23028356, 2012).
B-cell lymphoma (3 papers, 2020 to 2021). "NFKBIE aberrations are common genetic events in trans-b-cell malignancies, and NFKBIE deletion is a new marker of poor prognosis in primary mediastinal B-cell lymphoma (PMBL)." (PMID 33785008, 2021).
breast carcinoma (2 papers, 2021 to 2023). "Based on the results, it seemed that IL17B, NFKBIE and SERPINA3 mainly prompted the development of breast cancer." (PMID 33785008, 2021).
mantle cell lymphoma (2 papers, 2020 to 2024). Mantle cell lymphoma is a rare form of malignant non-Hodgkin lymphoma affecting B lymphocytes in the lymph nodes in a region called the ``mantle zone''. "Because mutations in other NF-κB pathway genes, including BIRC3, TRAF2, TRAF3, MAP3K14 and CARD11, have been associated with ibrutinib resistance in mantle cell lymphoma, we next investigated whether mutations in NFKBIE could also affect the response to ibrutinib treatment." (PMID 38486128, 2024).
schizophrenia (2 papers, 2017 to 2020). A major psychotic disorder characterized by abnormalities in the perception or expression of reality.
Alzheimer disease (1 paper, 2022). A progressive, neurodegenerative disease characterized by loss of function and death of nerve cells in several areas of the brain leading to loss of cognitive function such as memory and language. "Further validation was performed in another expression profile of AD, GSE33000, and the result implied high sensitivity and specificity of DGKG, MAP3K7IP2, NFKBIE, VIP, and PCCB for diagnosing Alzheimer’s disease (combined AUC = 0.9388)." (PMID 36092935, 2022).
autoimmune disease (1 paper, 2012). A disorder resulting from loss of function or tissue destruction of an organ or multiple organs, arising from humoral or cellular immune responses of the individual to their own tissue constituents. "As the majority of autoimmune disease loci have been implicated as eQTL, we speculated that variants in the NFKBIE and RTKN2 loci would influence gene function by regulating gene expression, in addition to changing the amino acid sequences." (PMID 23028356, 2012).
chronic graft versus host disease (1 paper, 2025). Chronic graft versus host disease (GVHD) is a complication that can occur after a stem cell or bone marrow transplant in which the newly transplanted donor cells attack the transplant recipient's body. "In another study that investigated lncRNA expression in chronic graft-versus-host disease, three lncRNAs (NONHSAT142151, NONHSAT040475 and FR118417) were found to strongly correlate with the expression of mRNAs related to the BCR signaling pathway (BTK, CD72, DAPP1, LILRB3, NFKBIE, RASGRP3)." (PMID 39940921, 2025).
gastric tumors (1 paper, 2016). "Integrated analysis of public data from gastric tumors revealed frequent (10 – 20 %) amplification of the genes NFKBIE, PTK2, and PIK3CA, each of which resides in an ERBB2-derived subpathway network." (PMID 26955870, 2016).
glioblastoma (1 paper, 2022). The most malignant astrocytic tumor (WHO grade IV).
leukemia (1 paper, 2024). A malignant (clonal) hematologic disorder, involving hematopoietic stem cells and characterized by the presence of primitive or atypical myeloid or lymphoid cells in the bone marrow and the blood. "To investigate how NFKBIE-mutations affect leukemia cell growth, we disrupted by CRISPR/Cas9 editing the NFKBIE gene in the murine TCL1-355-TKO cell line, which we recently established from the transgenic Eμ-TCL1 CLL model." (PMID 38486128, 2024). "In addition, we observed greater expression of PD-1 and TIGIT on T-cells from CLL patients with NFKBIE-mutated leukemia, further suggesting that NFKBIE mutations in CLL cells can promote T-cell exhaustion and contribute to escape from immune surveillance." (PMID 38486128, 2024). "Interestingly, we also observed a greater selection of NFKBIE-mutated murine leukemia cells in immunocompetent compared to immunodeficient mice, suggesting that the presence of NFKBIE mutations may impact the anti-tumor immune response." (PMID 38486128, 2024). "Analysis of leukemia cells isolated from PC, PB and spleen after 2 weeks of treatment showed a significantly greater increase in NFKBIE MAF in mice treated with ibrutinib compared to control mice in all investigated compartments." (PMID 38486128, 2024).
ovarian carcinoma (1 paper, 2025). A malignant neoplasm originating from the surface ovarian epithelium.
respiratory failure (1 paper, 2023). The significant impairment of gas exchange within the lungs resulting in hypoxia, hypercarbia, or both, to the extent that organ tissue perfusion is severely compromised. "In our study, the haplotype combination of the polymorphisms in different NF-κB inhibitors genes (NFKBIA,NFKBIE and NFKBIZ) have been associated with respiratory failure, time to clinical stability and higher punctuations in the CURB-65 score." (PMID 38143267, 2023).
tumor (11 papers, 2016 to 2025). "Pre-treatment NFKBIE and NFKBIE-related gene mutations in patient samples correlated with clinical outcomes including decreased tumor volume and progression free survival." (PMID 32708981, 2020). "However, our studies suggest the effects of NFKBIE variants may be from tumor cells, which are different from the RA or lymphoid malignancies." (PMID 32708981, 2020). "We show that NFKBIE mutations contribute to disease progression by increasing the growth rate of CLL cells stimulated with microenvironmental signals that activate NF-κB and by inducing alterations within the tumor microenvironment that can allow for immune evasion of the malignant B-cells." (PMID 38486128, 2024).
cancer (8 papers, 2017 to 2025). A tumor composed of atypical neoplastic, often pleomorphic cells that invade other tissues. "Yin and colleagues stratified BC patients into high and low risk cancers based on a seven gene expression assay (BATF, CD3D, HLA-DQB2, JUN, MAP2K6, NFKBIE, PAK1)." (PMID 40148963, 2025). "NFKBIE is a negative regulator of the NFkB signaling cascade, a biological pathway which is important in cancer and inflammation." (PMID 32708981, 2020). "According to the KEGG analysis, CHST11 may participate in PD‐L1 expression and PD‐1 checkpoint pathway in cancer by regulating genes TICAM2, LAT, TLR2, CD4, STAT3, NFKBIE and CD3D." (PMID 36062845, 2023).
infection (2 papers, 2025). The state of being infected such as from the introduction of a foreign agent such as serum, vaccine, antigenic substance or organism. "Pathways involved in chemokine receptor signaling were also significantly enriched, highlighting the recruitment of immune cells to the site of infection (NFKBIA, NFKBIB, NFKBIE, NFKBIZ, TNFAIP3, REL, BCL3)." (PMID 40634947, 2025).
NFKBIE also shares sentences with these, for which no sentence is quoted: Hodgkin's Disease (2 papers); prostate carcinoma (2); atherosclerosis (1); bipolar disorder (1); diffuse large B-cell lymphoma (1); epilepsy (1); Epstein-Barr virus infection (1); follicular lymphoma (1); genetic disorders (1); immune diseases (1); marginal zone lymphoma (1); meningitis (1); Obesity (1); Parkinson disease (1); pneumococcal meningitis (1); Richter syndrome (1); splenic marginal zone lymphoma (1); viral infection (1); Werner syndrome (1).